ZNF540 (zinc finger protein 540)
Description:
May act as a transcriptional repressor.
Synonyms: Nbla10512; DKFZp547B0714
Tractability: PROTAC: UniProt records ubiquitination sites on it; ubiquitination databases record sites on it.
Gene: Protein-coding gene on chromosome 19 (37,551,406 to 37,614,179, forward strand). Ensembl gene ENSG00000171817.
Subcellular location: Nucleus; Cytoplasm
Subcellular location (Human Protein Atlas): Nucleoplasm; Cytosol; Vesicles
Pathways (Reactome):
Gene expression (Transcription): Generic Transcription Pathway
Gene Ontology:
Molecular function: mRNA regulatory element binding translation repressor activity; protein binding; DNA-binding transcription factor activity, RNA polymerase II-specific; RNA polymerase II cis-regulatory region sequence-specific DNA binding
Biological process: negative regulation of DNA-templated transcription; negative regulation of translation; regulation of transcription by RNA polymerase II; negative regulation of gene expression; regulation of DNA-templated transcription
Cellular component: cytoplasm; cytosol; nucleoplasm; nucleus
Genetic constraint (gnomAD): Loss-of-function variants: 3 observed, 10.29 expected, observed/expected ratio (o/e) 0.29, 90% interval 0.13 to 0.75. The upper end of that interval is the gene's LOEUF score, 0.75, which puts it in group 3 of 6, group 1 being the genes least tolerant of losing a copy. Missense variants: 696 observed, 813.11 expected, observed/expected ratio (o/e) 0.86, 90% interval 0.8 to 0.91. Synonymous variants: 240 observed, 266.06 expected, observed/expected ratio (o/e) 0.9, 90% interval 0.81 to 1.
Homologues: Orthologues: chimpanzee ZNF540 (99% identical), macaque ZNF540 (96% identical), rabbit ZNF540 (76% identical). Paralogues in human: ZNF546 (54% identical), ZNF30 (51% identical), ZNF571 (47% identical), ZFP14 (47% identical), ZNF573 (47% identical), ZFP30 (46% identical), ZNF841 (45% identical), ZNF267 (45% identical), ZNF836 (44% identical), ZFP82 (44% identical), ZNF780B (43% identical), ZNF33B (43% identical), and 164 more.
Diseases named in the same sentence as ZNF540 in open-access papers:
ZNF540 is named in the same sentence as 11 diseases in open-access papers, as found by Europe PMC text mining. Sharing a sentence is not in itself a finding about the gene and the disease. The quoted sentences say what the papers report.
clear renal cell carcinoma (1 paper, 2022). "High promoter methylation was also reported in the case of ZNF418 in laryngeal squamous cell carcinoma and ZNF540 in clear cell renal cell carcinoma." (PMID 36547193, 2022).
liver cirrhosis (1 paper, 2023). "Persistent hypermethylation of the ZNF154 and ZNF540 genes, as well as CCL20 hypomethylation, were registered in tumor tissue in relation to both liver fibrosis and liver cirrhosis." (PMID 36923478, 2023).
lung carcinoma (1 paper, 2023). "In addition, the roles of SETDB2, SNAI3, SCML4, ZNF540, and ETV1 were validated in multiple datasets and human lung cancer cell lines." (PMID 37197420, 2023).
squamous cell lung carcinoma (1 paper, 2021). A carcinoma arising from squamous bronchial epithelial cells. "In a very recent study, findings show that ZNF540 and PGR were among top 267 down-regulated genes in the squamous cell lung cancer tissues compared to the adjacent normal tissues." (PMID 34061869, 2021).
tumor (4 papers, 2022 to 2023). "Some studies showed that CpG methylation changes in the ZNF540 through renal clear carcinoma tissue analysis associated with tumor aggressiveness and patient prognosis." (PMID 37197420, 2023). "Only for ZNF540 were differences in the fraction of macrophages observed, and patients with higher levels of ZNF540 displayed lower levels of infiltration of these cells in the tumor mass." (PMID 36547193, 2022). "Based on the UALCAN database, we observed a significant downregulation of ZFP28, ZNF132, ZNF418, ZNF426, ZNF540, and ZNF880 expression levels in primary tumor tissues compared to normal tissues." (PMID 36547193, 2022). "Thus, it may be hypothesized that the decreased expression of ZNF540 and ZNF418 may affect tumor formation not only through various oncogene-related pathways but also via interfering with the immune response." (PMID 36547193, 2022).
cancer (1 paper, 2022). A tumor composed of atypical neoplastic, often pleomorphic cells that invade other tissues. "The expression level of ZNF540 was also assessed in four different molecular cancer clusters." (PMID 36547193, 2022).
ZNF540 also shares sentences with these, for which no sentence is quoted: glioblastoma (1 paper); head and neck squamous cell carcinoma (1); laryngeal squamous cell carcinoma (1); liver fibrosis (1); lung adenocarcinoma (1).